TICAM1 (TIR domain containing adaptor molecule 1)
Description:
Involved in innate immunity against invading pathogens. Adapter used by TLR3, TLR4 (through TICAM2) and TLR5 to mediate NF-kappa-B and interferon-regulatory factor (IRF) activation, and to induce apoptosis. Ligand binding to these receptors results in TRIF recruitment through its TIR domain. Distinct protein-interaction motifs allow recruitment of the effector proteins TBK1, TRAF6 and RIPK1, which in turn, lead to the activation of transcription factors IRF3 and IRF7, NF-kappa-B and FADD respectively. Phosphorylation by TBK1 on the pLxIS motif leads to recruitment and subsequent activation of the transcription factor IRF3 to induce expression of type I interferon and exert a potent immunity against invading pathogens. Component of a multi-helicase-TICAM1 complex that acts as a cytoplasmic sensor of viral double-stranded RNA (dsRNA) and plays a role in the activation of a cascade of antiviral responses including the induction of pro-inflammatory cytokines (By similarity).
Synonyms: TICAM-1; MyD88-3; PRVTIRB; TRIF; MGC35334; IIAE6
Tractability: PROTAC: UniProt records ubiquitination sites on it; ubiquitination databases record sites on it.
Gene: Protein-coding gene on chromosome 19 (4,815,932 to 4,831,712, reverse strand). Ensembl gene ENSG00000127666.
Subcellular location: Cytoplasmic vesicle, autophagosome; Cytoplasm, cytosol; Mitochondrion
Subcellular location (Human Protein Atlas): Nucleoli; Nucleoplasm; Plasma membrane
Pathways (Reactome):
Immune System: Activation of IRF3, IRF7 mediated by TBK1, IKKε (IKBKE); IKK complex recruitment mediated by RIP1; IRAK2 mediated activation of TAK1 complex upon TLR7/8 or 9 stimulation; MyD88-independent TLR4 cascade; RIP-mediated NFkB activation via ZBP1; Regulation of TBK1, IKKε (IKBKE)-mediated activation of IRF3, IRF7; Regulation of TBK1, IKKε-mediated activation of IRF3, IRF7 upon TLR3 ligation; TICAM1, RIP1-mediated IKK complex recruitment; TICAM1,TRAF6-dependent induction of TAK1 complex; TICAM1-dependent activation of IRF3/IRF7; TLR3-mediated TICAM1-dependent programmed cell death; TRAF6-mediated induction of TAK1 complex within TLR4 complex; TRIF-mediated programmed cell death; Toll Like Receptor 3 (TLR3) Cascade
Disease: TICAM1 deficiency - HSE; TRAF3 deficiency - HSE
Programmed Cell Death: Caspase activation via Death Receptors in the presence of ligand
Gene Ontology:
Molecular function: molecular adaptor activity; protein binding; protein kinase binding; signaling adaptor activity
Biological process: positive regulation of canonical NF-kappaB signal transduction; positive regulation of type I interferon production; response to exogenous dsRNA; toll-like receptor 3 signaling pathway; toll-like receptor 4 signaling pathway; toll-like receptor signaling pathway; TRIF-dependent toll-like receptor signaling pathway; cellular response to lipopolysaccharide; cellular response to oxidised low-density lipoprotein particle stimulus; innate immune response; lipopolysaccharide-mediated signaling pathway; positive regulation of autophagy; positive regulation of cytokine production involved in inflammatory response; positive regulation of gene expression; positive regulation of myeloid dendritic cell cytokine production; TRIF-dependent toll-like receptor 4 signaling pathway; cell surface receptor signaling pathway; signal transduction
Cellular component: early endosome; endosome; endosome membrane; ripoptosome; cytosol; mitochondrion; autophagosome
Genetic constraint (gnomAD): Loss-of-function variants: 0 observed, 0.68 expected, observed/expected ratio (o/e) 0, 90% interval 0 to 1.8. That is too few expected variants to judge how well the gene tolerates losing a copy. Missense variants: 895 observed, 923.94 expected, observed/expected ratio (o/e) 0.97, 90% interval 0.92 to 1.02. Synonymous variants: 439 observed, 410.56 expected, observed/expected ratio (o/e) 1.07, 90% interval 0.99 to 1.16.
Homologues: Orthologues: macaque TICAM1 (93% identical), chimpanzee TICAM1 (74% identical), pig TICAM1 (71% identical), guinea pig TICAM1 (57% identical), mouse Ticam1 (57% identical), rat Ticam1 (54% identical), dog TICAM1 (50% identical).
Diseases named in the same sentence as TICAM1 in open-access papers:
TICAM1 is named in the same sentence as 36 diseases in open-access papers, as found by Europe PMC text mining. Sharing a sentence is not in itself a finding about the gene and the disease. The quoted sentences say what the papers report.
viral infection (9 papers, 2014 to 2024). "PRRs and these adaptor molecules are also involved in ARDS caused by viral infection, and it has been reported that TICAM-1 had a protective role in ARDS caused by SARS-CoV, showing increased mortality, weight loss, and reduced lung function in Ticam-1 KO mice." (PMID 34819358, 2022). "Thus, such a cross-regulation among PRRs (TLR2 and TLR3) causing subsequent downregulation of TLR3 and TICAM1 may result in weakened innate immunity against viral infections." (PMID 29449840, 2018). "TICAM-1 is a protein known to interact with the cytoplasmic tail of Toll-like receptor 3 (TLR3) and is reported to regulate antiviral activities in several virus infection models." (PMID 34769416, 2021).
COVID-19 (8 papers, 2021 to 2026). A disease caused by infection with severe acute respiratory syndrome coronavirus 2. "Among the extracted ultra-rare variants there was a group of genes, such as TLR3, TLR7 and TICAM1, already shown to be directly involved in the Mendelian-like forms of COVID-19." (PMID 34889978, 2022). "In the same work, patients harboring TICAM1 or TBK1 deficiency were tested to evaluate IFN-α levels during the acute phase of COVID-19." (PMID 35062298, 2022). "We demonstrate that COVID-19 patients possess subtly elevated TICAM-1 expression and NF-kappaB signaling in the hippocampus, the latter of which is the direct effect of the TLR-TICAM-1 signaling cascade." (PMID 39154174, 2024). "It has been found that about 3.5% of COVID-19 patients had known autosomal-recessive (AR) deficiencies [interferon regulatory factor 7 (IRF7) and IFNAR1] and autosomal-dominant deficiencies (AD) [toll-like receptor 3 (TLR3), UNC93B1, TICAM1, TBK1, IRF3, IRF7, IFNAR1, and IFNAR2]." (PMID 34335535, 2021). "In this sense, IFN polymorphisms or polymorphisms of the molecules in charge of signaling for their production, such as IRF3, IRF7, TICAM1, TBK1, and STAT2, have also been related to poor prognosis of COVID-19 patients." (PMID 35062298, 2022). "Most striking was the under-expression of genes involved in viral recognition (e.g. TLR7, UNC93B, RIG-I/DDX58), as well as genes encoding downstream signaling molecules and transcription factors (e.g. TRIF/TICAM1, MYD88, IRF7), with the notable exception of IRF4, in COVID-19 compared to INFL." (PMID 34135895, 2021).
vitiligo (3 papers, 2016 to 2022). Generalized well circumscribed patches of leukoderma that are generally distributed over symmetric body locations and is due to autoimmune destruction of melanocytes. "Additionally, genes related to innate immunity including NALP1, TICAM1, IFIH1 are recognized as vitiligo susceptibility genes." (PMID 35884944, 2022). "Viral factor has been implicated in the etiopathogenesis of vitiligo, we speculate that TICAM1 might act as a viral factor in the pathogenesis of vitiligo." (PMID 26870082, 2016). "TICAM1, also known as TIR domain-containing adaptor-inducing IFN-b, which encodes Toll-like receptor adaptor molecule 1, mediates the innate immune response to viral pathogens, might act as a viral factor in the pathogenesis of vitiligo." (PMID 35884944, 2022).
breast carcinoma (2 papers, 2022). "Although TICAM1 has been extensively studied in inflammation responses and some cancers such as prostate cancer, breast cancer, and colorectal cancer, there is still a lack of knowledge about the role of TICAM1 in WT progression." (PMID 35933370, 2022).
lupus (2 papers, 2017 to 2025). "The importance of interferons was highlighted in our previous results on the TLR4 signaling pathway, where TLR4, TICAM1, TICAM2, TBK1, IRF3, IFNA1, and IFNA2 mRNAs showed changes in the murine lupus-like models." (PMID 29349090, 2017).
Wilms tumor (2 papers, 2022). An embryonal neoplasm characterized by the presence of epithelial, mesenchymal, and blastema components. "However, the role of TICAM1 in Wilms tumor (WT) is rarely known." (PMID 35933370, 2022).
Encephalopathy (1 paper, 2023). Encephalopathy is a term that means brain disease, damage, or malfunction. "Similar dualities for the STAT1 (M600555), TNFRSF13B (M6049097), and TICAM1 (M607601) genes may apply since the first two are associated with immunodeficiency disorders and the last confers susceptibility to encephalopathy from herpes virus infection." (PMID 37504295, 2023).
hepatitis B virus infection (1 paper, 2021). A viral infection caused by the hepatitis B virus. "Conversely, TICAM-1 is dispensable for defending hepatitis B virus infection in TICAM-1−/− mice." (PMID 34769416, 2021).
lung carcinoma (1 paper, 2025). "TLR3/4 activation results in the upregulation of chemokines CCL2/MCP-1 and immunosuppressive factors VEGFA and MMP2, which collectively promotes lung cancer invasion and metastasis through the adaptor protein TICAM1/TRIF and the activation of downstream MAPK/NF-κB signaling pathway." (PMID 41293166, 2025).
multiple myeloma (1 paper, 2022). "Previous studies proved that activating TLR3/TICAM1 signaling could suppress multiple myeloma progression." (PMID 35933370, 2022).
oral cancers (1 paper, 2018). "The 14-3-3ζ proteins promote immunity by regulating TLR-3 signaling through TICAM-1 pathway and immune responses through Stat3 signaling in oral cancers." (PMID 29966317, 2018).
polyposis (1 paper, 2017). "If this is the case, both MyD88 and TICAM-1 pathways participate in polyposis under the presence of complex innate stimulation." (PMID 29041928, 2017).
tumor (17 papers, 2016 to 2025). "Perilipins are structural proteins associated with lipophagy and lipid droplet integrity, and their overexpression is associated with tumor aggressiveness, while TICAM1 participates in immune and inflammation responses to malignant cells." (PMID 36552033, 2022). "Downregulated TICAM1 may be involved in tumor associated immune responses and tumor progression." (PMID 35933370, 2022). "It has been reported that TLR3/TICAM1 signaling is involved in tumor cell RIP3-dependent necroptosis, which contributes to immune effector-mediated tumor elimination." (PMID 36936916, 2023). "DMBA3-4 tumor rejection persisted in Ifng–/– (IfngKO); Klrk1–/– (Klrk1KO); Sting–/– (StingKO); Ifnar1–/– (Ifnar1KO); Ticam1–/–,Myd88–/– (Ticam1KO Myd88KO); and Ncr1iCre,ROSADTR mice." (PMID 37843274, 2023). "The results indicated that the expression of TICAM1, tumor stage, adverse event rate and gender were independent prognosis factors of WT." (PMID 35933370, 2022). "The expression of TICAM1 was negatively correlated with tumor-infiltrating macrophages and B cells and positively correlated with DC infiltration." (PMID 36588538, 2022). "ARNAX, a TLR3 agonist, promoted full priming and proliferation of CTLs and enhanced CD8+ T cell infifiltration into the tumor site through TLR3-TIR domain-containing adaptor molecule-1 (TICAM-1)-IRF3-IFN-β axis in DCs." (PMID 33469538, 2020). "Intestinal epithelial cells express TLRs which utilize two adaptors, MyD88 and/or TICAM-1, as well as immune cells and tumor cells in mice." (PMID 29041928, 2017). "RNA adjuvant therapy mimicking dsRNA by Poly(I:C) modulated tumor infiltrating myeloid cells via TLR3/TICAM-1 pathway from tumor-supportive to tumor-suppressive." (PMID 27886105, 2016). "Not only a TLR3-specific (TICAM-1-dependent) signal but also TLR2 (MyD88) signal in DC triggered the expansion of CD11c+ CD8+ T cells in tumor-bearing mice." (PMID 27619885, 2016). "This suggests that poly(I:C)-induced signaling contributes to immune cell recruitment to ESCC cells via the TLR3/TICAM-1 pathway, though confirming activation of natural killer cells and recruitment of lymphocytes to the tumor microenvironment in ESCC will require further studies." (PMID 40029556, 2025). "Besides, according to basic pathway mechanisms and bioinformatics prediction results, downregulated TICAM1 is likely to promote the generation of M2 macrophages and weaken immune responses to tumor cells." (PMID 35933370, 2022). "TLR3-TICAM1 signaling is an inflammation response pathway, and in WT, downregulated TICAM1 may prevent inflammation responses to tumor cells." (PMID 35933370, 2022). "Furthermore, IRGs associated with tumor progression, including PDGFA, ITPR3, SLPI, TICAM1, and GATA4, were identified." (PMID 36588538, 2022). "Intraperitoneal injection of Poly(I:C) one day before irradiation of LLC-OVA tumor enhanced the tumor shrinkage and, by the use of TLR3- and TICAM-1-deficient mice, the authors demonstrated that the effect was dependent on the activation of TLR3-TICAM-1 pathway." (PMID 33147700, 2020). "However, TLR3/TICAM-1 signals convert these myeloid cells to tumoricidal effectors in tumor microenvironment." (PMID 29041928, 2017). "Thus, the incidence of tumor formation is high in the middle and distal intestine of ApcMin/+Ticam1−/− mice compared to ApcMin/+ mice." (PMID 29041928, 2017). "Thus, tumor-related inflammation was induced to a greater extent in the intestine of ApcMin/+Ticam1−/− mice than in ApcMin/+ mice." (PMID 29041928, 2017). "Moreover, they suggest the TLR3/TICAM-1 may contribute to previously reported CXCL10-mediated recruitment of CXCR3-positive lymphocytes to the tumor microenvironment." (PMID 40029556, 2025). "TICAM1 may up-regulate and down-regulate the expression of different genes via the same pathway in different tumors, thus forming diversified gene expression profiles and playing divergent roles in tumor development and evolution." (PMID 35933370, 2022).
tumor (continued). "Furthermore, injection of polyinosinic:polycytidylic acid (polyI:C) into Lewis lung carcinoma tumor–implanted mice to activate the TLR3/Toll–IL1 receptor domain–containing adaptor molecule 1 (TICAM-1) switches tumor-promoting macrophages into tumor suppressors." (PMID 28467800, 2017). "The results showed that the expression levels of PYGB, IFNGR2, TICAM1, STAT6 and VPS4B in CHOL tissues showed an overall upward trend compared with non-tumor hepatobiliary duct tissues." (PMID 36936916, 2023). "Our prognostic signature consists of five genes, PYGB, IFNGR2, TICAM1, STAT6, and VPS4B, each of which plays a critical role in necroptosis and tumor progression." (PMID 36936916, 2023). "In our study, TICAM1 was highly expressed in the CHOL group and was positively correlated with resting central memory CD4+ T cells and NK cell activation, suggesting that the TICAM1 gene product is involved in the tumor microenvironment." (PMID 36936916, 2023). "It was found that TICAM1 expression levels were not statistically significantly correlated with all clinicopathological factors, except the tumor stage." (PMID 35933370, 2022).
infection (11 papers, 2015 to 2023). The state of being infected such as from the introduction of a foreign agent such as serum, vaccine, antigenic substance or organism. "Similarly, enterovirus 68 infection inhibits the ability of HeLa cells to respond to poly(I:C) and this is associated with cleavage of TICAM-1 and reduced IRF-3 activation." (PMID 26437794, 2015). "ii) TLR3, a receptor for viral dsRNA, displayed a strong reduction in influenza virus and icMERS infection, while TICAM1, TRAF1, TRAF2, TRAF3 and TRAF6, adaptors responsible for TLR3, changed in an opposite direction with TLR3." (PMID 34248940, 2021). "IEIs of TLR3-, IRF7-, UNC93B1-, TICAM1-, TBK1-, and interferon alpha and beta receptor subunit 1 (IFNAR1)-dependent type I interferon immunity have been described to underlie life-threatening COVID-19 pneumonia in patients with no prior severe infection." (PMID 37559153, 2023).
cancer (5 papers, 2014 to 2025). A tumor composed of atypical neoplastic, often pleomorphic cells that invade other tissues. "Immune cells and cytokines facilitate the occurrence, progression, metastasis, and relapse of cancers, so an immune infiltration algorithm is used to evaluate the association of TICAM1 with immune infiltration and the distribution of immune cells." (PMID 35933370, 2022). "The pan-cancer analysis results show that TICAM1 is either highly or lowly expressed in other cancers, but in the WT TARGET cohort and external validation cohort GSE66405, it is confirmed that TICAM1 expression in WT tissue is significantly lower than that in normal tissue (p < 0.05)." (PMID 35933370, 2022). "TICAM1 has been found to participate in immune responses and promote apoptosis in other cancers." (PMID 35933370, 2022). "Thus, if cancer and normal cells would differ with regard to TICAM-1 or IRF-3, then such a virus could potentially target specifically cancer cells rather than normal cells." (PMID 28548066, 2014). "The ability of poly(I:C) to suppress cancer cell proliferation was unaffected by MAVS or TICAM-1 knockdown (data not shown)." (PMID 40029556, 2025).
adenocarcinoma (1 paper, 2012). A common cancer characterized by the presence of malignant glandular cells. "The TICAM2 physically bridged toll like receptor-4 (TLR4) with TICAM1 and the TLR4 partially regulated by the HIF during adenocarcinoma." (PMID 23122428, 2012).
infectious disease (1 paper, 2022). A disorder directly resulting from the presence and activity of a microbial, viral, or parasitic agent in humans. "Thus, the cross talk between TLR3 and IL-17A signaling via TICAM-1 is expected to be important to understand the pathogenesis of those serious infectious diseases, including recent coronavirus disease 2019." (PMID 34819358, 2022).
TICAM1 also shares sentences with these, for which no sentence is quoted: pneumonia (2 papers); prostate carcinoma (2); acute monocytic leukemia (1); Autoimmunity (1); breast tumors (1); colitis (1); colorectal cancer (1); demyelination (1); encephalitis (1); endometriosis (1); gastric cancer (1); immunodeficiency disorders (1); influenza (1); iron deficiency (1); neuroblastoma (1); pertussis (1); primary immunodeficiency (1); SARS-CoV infection (1); thyroid cancer (1).